RNU6-584P (RNA, U6 small nuclear 584, pseudogene)
Gene: Small nuclear RNA gene on chromosome 1 (37,885,023 to 37,885,117, forward strand). Ensembl gene ENSG00000222282.
Homologues: Orthologues: chimpanzee U6 (100% identical), macaque U6 (99% identical), rat LOC120102571 (81% identical), pig U6 (79% identical), dog U6 (77% identical), mouse Gm55402 (49% identical). Paralogues in human: RNU6-1083P (89% identical), RNU6-393P (88% identical), RNU6-797P (88% identical), RNU6-1145P (87% identical), RNU6-16P (87% identical), RNU6-35P (87% identical), RNU6-41P (87% identical), RNU6-1031P (86% identical), RNU6-1047P (86% identical), RNU6-106P (86% identical), RNU6-1091P (86% identical), RNU6-1152P (86% identical), and 1282 more.